PALB2 (partner and localizer of BRCA2)
Diseases named in the same sentence as PALB2 in open-access papers (continued):
Sharing a sentence is not in itself a finding about the gene and the disease.
breast cancer (continued). "Similarly, PALB2 c.3113G>A was identified in 5/1,403 (0.4%) unselected breast cancer cases and 0/764 (0%) unaffected controls in the Australian population." (PMID 23448497, 2013). "Neither of these two high-grade serous carcinoma PALB2 mutation-carriers (diagnosed at ages 51 and 58) had a personal history of breast cancer, although the ovarian cancer case diagnosed at age 58 years had a family history of breast and/or ovarian cancer." (PMID 23302520, 2013). "The first-degree female relatives of these carriers demonstrated significantly higher incidence of breast cancer than relatives of noncarriers, indicating that pathogenic PALB2 mutations confer an estimated 5.3-fold increase in risk." (PMID 23586058, 2013). "Given the potential benefits versus harms of this testing, the result of our study suggest that PALB2 c.1592delT should be a routine part of the genetic counseling protocol for Finnish high-risk breast cancer cases tested negative for mutations in BRCA1/BRCA2." (PMID 23941127, 2013). "The goal of this study was to determine the prevalence of PALB2 mutations in a population of BRCA1/BRCA2 negative breast cancer patients selected from either a personal or family history of pancreatic cancer." (PMID 23935836, 2013). "Our data shows that PALB2 germline mutations are rare, and are associated with family history of breast cancer in some, but not all families." (PMID 23977390, 2013). "In contrast, no PALB2 variants were reported in two other independent studies involving 99 and 21 independently ascertained breast cancer families of French Canadian descent." (PMID 23302520, 2013). "Initial reports of comprehensive screening of all of the protein encoding exons of PALB2, identified no variants in 38 breast cancer families, where 22 families had a prior probability of greater than 10% of harboring a BRCA1 or BRCA2 mutation." (PMID 23302520, 2013). "The breast cancer susceptibility and Fanconi proteins FANCD1/BRCA2, the partner of BRCA2 (PALB2/FANCN), a helicase associated with BRCA1 (FANCJ/BACH1), and several newly identified components including FAN1, FANCO/RAD51C, and FANCP/SLX4 participate in the pathway to respond to and repair DNA damage." (PMID 22693661, 2012). "Heterozygous mutations in FA genes have been associated previously with increased breast cancer risk, and, conversely, bi-allelic mutations in breast cancer-associated genes BRCA2, BRIP1, PALB2, and RAD51C have been identified in persons with FA or FA–like syndromes." (PMID 23028381, 2012). "We find that DNA binding by BRCA2 is critical when a BRCA2 peptide is deficient in binding another breast cancer suppressor, PALB2, but not when the peptide can bind PALB2, suggesting alternative mechanisms of activity." (PMID 22194698, 2011). "It has recently been established that mutations in two other FA genes may confer an increased risk of breast cancer; the increased risk for FANCJ/BRIP1 is around 2-fold, and that for FANCN/PALB2 is probably 2–4 fold, but may be higher for certain mutations." (PMID 18786261, 2008). "PALB2 appears not to be a significant factor in high-risk breast cancer families in Iceland and the 1592delT mutation is not seen to be associated with breast cancer in Iceland." (PMID 18637200, 2008).
breast cancer (continued). "However, they describe two cases who have PVs in moderate to low breast cancer risk genes (ATM/PALB2; case 119, ATM/FANCA; case 122) with bilateral breast cancer at age 35 and breast cancer at age 35 respectively – highlighting multiple and young onset cancers." (PMID 39843919, 2025). "In addition, the AFR population also exhibited a higher frequency of additional variants associated with breast cancer predisposition: BRCA2 (OR 2.24 [95% CI (1.31, 3.84), logistic regression p = 0.0031]) and PALB2 (OR 2.92 [95% CI (2.04, 4.19), logistic regression p = 5.8 × 10−9])." (PMID 40394000, 2025). "Although CNA on chromosome 16 is common, no PALB2 loss has been shown in breast cancer patients." (PMID 37628606, 2023). "To investigate whether MBC and FBC risk might be at least in part due to different genes, we then examined their mutability in a population of high-risk breast cancer women without BRCA1/BRCA2/PALB2 PV/LPV detected on the same 585-gene panel analysis." (PMID 37762649, 2023). "Interestingly, in breast cancer, higher PALB2 expression (which may be due to amplification of the 16p12.2 locus) is associated with lower overall survival (at p < 0.01) in stage III patients." (PMID 37628606, 2023). "To study the specificity of this MBC PV/LPV profile, we examined whether variants in the same genes could be detected in a female breast cancer (FBC) cohort without BRCA1/BRCA2/PALB2 PV/LPV." (PMID 37762649, 2023). "The BC susceptibility genes involved in breast cancer which cause moderate risk are BRIP1, CHEK2, ATM, RAD51C, and PALB2." (PMID 36873936, 2023). "Moreover, recent data have also suggested that pathogenic mutations in FANCN/PALB2, another established breast cancer predisposition gene, might also confer increased susceptibility to CRC." (PMID 35330396, 2022). "In addition, high PALB2 expression leads to a poor prognosis in advanced breast cancer." (PMID 36158641, 2022). "Our conclusion that EARS2 expression might be a risk factor for pancreatic cancer in breast cancer patients with PALB2 mutations is based on mRNA expression since there were only 2 pancreatic cancers and no breast cancers with a PALB2 mutation." (PMID 35779338, 2022). "Furthermore, the reversion mutations were not only detected in BRCA1/2, but also in other HRR pathway genes including RAD51C, RAD51D, and PALB2 in ovarian, prostate, and breast carcinomas as a mechanism of acquired resistance to platinum-based chemotherapies and PARPIs." (PMID 35785170, 2022). "Heterozygous pathogenic germline variants in PALB2 have been associated with an increased risk of breast cancer which approaches that seen with variants in BRCA2, in the order of 48–63%, with increased risks for those patients with a family history of breast cancer." (PMID 34771713, 2021).
breast cancer (continued). "PALB2 is associated with an increased risk of breast cancer, and the absolute risk for PALB2 carriers by 70 years of age is 33% in the absence of a breast cancer family history but up to 58% for a female carrier with two or more first-degree relatives with breast cancer diagnosed by 50 years of age." (PMID 33413596, 2021). "Indeed, 10-year survival was 48% in PALB2 mutation carriers with breast cancer vs. 74.7% in non-mutation carriers with breast cancer and 72% in BRCA1 mutated patients." (PMID 33718150, 2021). "This is in keeping with PGVs of PALB2 being relatively rare and associated with high-risk breast cancer predisposition, and so would be less likely to be detected in excess in our non-high-risk breast cancer cases." (PMID 34113003, 2021). "Most PALB2-HET breast cancers were not accompanied by PALB2 somatic mutations, LOH, or hypermethylation, which supported the haploinsufficiency hypothesis." (PMID 33193564, 2020). "Regarding PALB2 (Partner And Localizer of Breast Cancer Type 2 susceptibility protein (BRCA2)), mutations in this gene have been associated with increased risk of BC." (PMID 31817194, 2019). "As an exploratory, hypothesis-generating analysis, we compared the genomic profiles of invasive breast cancers developing in the context of pathogenic PALB2 germline mutations with or without loss of the PALB2 wild-type allele." (PMID 31428676, 2019). "PALB2 may also act independently from BRCA2 to regulate the metastasis of the breast cancer cells." (PMID 29321957, 2018). "No other loss-of-function PALB2 mutation was identified in this early-onset breast cancer study." (PMID 29422015, 2018). "Several FA genes (FANCD1/BRCA2, FANCN/PALB2, FANCJ/BRIP1, FANCO/RAD51C, and FANCS/BRCA1) are high- or moderate-risk breast or ovarian cancer susceptibility genes and previous studies have connected also heterozygous FANCM mutations with breast cancer predisposition." (PMID 28702895, 2017). "However,other genes, such as ATM, PALB2, BRIP1, CHEK, BARD1, while lower in frequency, may also increase breast cancer risk." (PMID 29093764, 2017). "A longitudinal study showed that, by 70 years of age, the absolute breast-cancer risk for female PALB2 mutation carriers ranges from 33% (95% CI, 25 to 44) for those with no family history of breast cancer to 58% (95% CI, 50 to 66) for those with a family history." (PMID 26824983, 2016). "Interestingly, women with PALB2 mutations from families with a history of breast cancer had substantially greater breast cancer risk than women with PALB2 mutations but no family history." (PMID 27716388, 2016).
breast cancer (continued). "Currently, prospective data related to the clinical outcomes of PALB2 mutation carriers is lacking and very little information (beyond mutation penetrance) is available to guide clinical management for carriers (affected and unaffected by breast cancer)." (PMID 27099641, 2016). "In our study, the four cases of male breast cancer had no detectable PALB2 mutations." (PMID 26489409, 2015). "In addition, the risk was higher for PALB2 mutation carriers with a family history of breast cancer compared to no family history suggesting that the risk is influenced by other genetic factors and/or environmental factors." (PMID 26082817, 2015). "Additionally, while some studies have suggested an earlier age of onset of pancreatic or breast cancer in those with PALB2 mutations in the setting of FPC, recent studies have not observed similar findings." (PMID 24624093, 2014). "The aim of the current study was to analyze whether female index individuals of breast cancer families who had tested negative for germline mutations in BRCA1/BRCA2 as part of genetic counseling services should be offered mutation testing for PALB2 c.1592delT." (PMID 23941127, 2013). "Most previous studies have not found evidence that PALB2 mutations were associated with hormone-receptor negative breast tumours, but one study reported that carriers of a Finnish founder mutation in PALB2 had triple negative breast cancer significantly more often than other breast cancer patients." (PMID 23110154, 2012). "In addition to breast cancer, heterozygous mutations in PALB2 also increase the risk of pancreatic cancer but not prostate cancer." (PMID 23176254, 2012). "However, it is still possible that BCoR-L1 could be involved in breast cancer predisposition as a moderate- or low-penetrance risk gene, as has been found with CHEK2, BRIP1, and PALB2 in large studies of BRCAX cases and controls." (PMID 17697391, 2007). "Compared to the sporadic group, triple-negative breast cancers were overrepresented among BRCA1 carriers (23.6% vs. 75.5%; p < .001), and family history of breast cancer was significantly more frequent among BRCA1, BRCA2, and PALB2 carriers (all p < .05)." (PMID 42252839, 2026). "For breast cancer, there were 6 genes with a posterior probability > 0.9: BRCA2, BRCA1, PALB2, CHEK2, ATM, and MAP3K1." (PMID 40073867, 2025). "Overall, 309 affected BRCA1/2 and PALB2 carriers with a median age of 43 years at breast cancer diagnosis (range, 19–80 years) were included; 160 (51.8%) BRCA1, 130 (42.1%) BRCA2, and 19 (6.1%) PALB2 carriers." (PMID 40275390, 2025). "In our study of 309 affected BRCA1/2 and PALB2 carriers with operable breast cancer, the receipt of chemotherapy following an index breast cancer diagnosis was 70% overall but varied from 57% in BRCA2 carriers to upwards of 80% in BRCA1 and PALB2 carriers." (PMID 40275390, 2025). "Chemotherapy was administered in 70.9% of index breast cancer cases diagnosed in BRCA1/2 and PALB2 carriers." (PMID 40275390, 2025). "PALB2 is an integral component of the BRCA complex required for HRR and an important mediator in hereditary breast cancer pathogenesis." (PMID 40948682, 2025).
breast cancer (continued). "The PALB2 carriers were predominantly HR-positive (75%, 9/12), and HER2-negative (83.3%, 10/12) breast cancer." (PMID 38914840, 2024). "While BRCA1/2 mutations are the standard in clinical testing, other HRR pathway genes, such as PALB2 and RAD51C, have potential applications in determining breast cancer treatment." (PMID 38397152, 2024). "As a comparison, we included the analysis of RAD51 foci in primary tumor samples from patients with untreated breast cancer with germline PVs in BRCA1, BRCA2, and PALB2, which showed a high prevalence of HRD (92.2% [95 of 103]), as expected." (PMID 38648056, 2024). "In contrast, HER2-/HR- breast cancer, also known as triple-negative breast cancer (TNBC), exhibited a prevalence of 0.41%, representing 8.3% (1/12) of PALB2 carriers." (PMID 38914840, 2024). "In breast cancer cells, depletion of BRCA1 or PALB2 diminishes the anti-proliferative effect exerted by ATRA." (PMID 38360674, 2024). "Nonetheless, other genes in the HRR pathway, such as the RAD51c, PALB2, BRIP1, and BARD1 gene defects, have also been shown to impact breast cancer progression and outcomes." (PMID 38397152, 2024). "The current panel of genes with strong evidence for use in clinical practice include PALB2, CHEK2, ATM, RAD51C and RAD51D with additional genes such as BARD1 (breast cancer) and BRIP1 (ovarian cancer) continuing to emerge." (PMID 39107016, 2024). "For BRCA1, peak breast cancer incidence occurs between 41 and 50 years, whereas for BRCA2 and PALB2, peak incidence occurs between 51 and 60 years of age." (PMID 38248108, 2024). "In the breast cancer cell line MCF-7, ATRA signaling requires BRCA1 and PALB2 for the modulation of all the retinoid regulated transcriptome including the classical retinoid-responsive HOXs (Homeobox genes) genes." (PMID 38360674, 2024). "In addition, identifying the presence of recurrent and/or none PALB2 PVs/LPVs will help in understanding the contribution to breast cancer and ovarian cancer risk and tailor the best preventive and treatment option of PALB2 carriers from Middle Eastern ethnicity." (PMID 37169825, 2023). "In this regard, thequantitative assessment of Partner and localizer of BRCA2 (PALB2) and BRCA1Interacting Helicase 1 (BRIP1) genes expression in the breast cancer cell lineunder the treatment of Tamoxifen (TAM) was executed in this study." (PMID 39430039, 2023). "With ever-expanding familial databases and collaboration, further biomarkers in PALB2 and CHEK2 familial breast cancers should be explored, with some small case series showing some benefit of platinum-based chemotherapy in these cancers." (PMID 36831687, 2023). "Among participants with family history of breast cancer, PTVs in ATM (p-value = 0.002), BRCA2 (p-value = 0.005), BRCA1 (p-value = 0.046), PALB2 (p-value = 0.039) and RAD50 (p-value = 0.044) were significantly associated with increased risk of breast cancer." (PMID 37790698, 2023). "Germline PV of other genes of the HR, especially PALB2, CHEK2, and ATM, were found in 0.5–1.5% of patients with unselected breast cancers, and were obviously more frequent among patients with family breast cancer history." (PMID 35158866, 2022).